ESR1 (estrogen receptor 1)
Diseases named in the same sentence as ESR1 in open-access papers (continued):
Sharing a sentence is not in itself a finding about the gene and the disease.
breast cancer (continued). "Herein we build on our original report by contrasting the functional, transcriptional, and pharmacological properties of the ESR1-e6>YAP1 fusion with additional ESR1 gene fusion events identified by RNA-seq of both early-stage and metastatic ER+ breast cancers." (PMID 30089255, 2018). "Within the subtypes of breast cancer, those identified as triple negative for expression of estrogen receptor α (ESR1), progesterone receptor (PR) and human epidermal growth factor 2 (HER2), account for 10–20% of breast cancers, yet result in 30% of global breast cancer-associated deaths." (PMID 30373175, 2018). "Growth regulation by estrogen in Breast Cancer 1 (GREB1) (fold change=-2.81 in our data) interacts with estrogen receptor (ER) in half of ER positive primary breast cancers; however, how could it interact with ESR1 in TNBC remains unknown." (PMID 30175120, 2018). "GREB1 (Growth regulation by estrogen in breast cancer 1) is an ESR1 (estrogen receptor 1)-upregulated protein which may mediate estrogen action." (PMID 29973689, 2018). "Also, a pattern of ESR1 fusions is emerging in metastatic ER+ breast cancer, in which the first six exons of ESR1 are fused in-frame to C-terminal partner sequences provided by the partner gene." (PMID 30525098, 2018). "Interestingly, one module (179 genes) associated with NF1 shallow deletion copy number status contained several genes that are considerably important in both ER+ breast cancers and endocrine resistance, including ESR1." (PMID 30182054, 2018). "The methylation of the promoter region in ESR1 gene is observed through DNA methyl transferases (DNMTs) that insert a methyl group to cytosine of CpG residues in the ERα -negative breast cancers in contrast to the unmethylation in the transcriptional region of ERα -positive breast cancers." (PMID 30375428, 2018). "Any possible correlation between ESR1 and GREB1 expression was also examined to determine whether GREB1 correlates with ESR1 in ovarian cancer, as reported in breast cancer." (PMID 29973689, 2018). "XBP1 promotes the growth of ESR1+ breast cancers by regulating ESR1 signaling." (PMID 30248920, 2018). "Until now, the presence of circulating ESR1 mutations at the end of adjuvant treatment by AI in early breast cancer had never been clearly established." (PMID 29769099, 2018). "In the present study, enhanced YBX1 expression was mostly correlated with enhanced expression of genes involved in cell growth, cell cycle, survival and DNA synthesis, as well as decreased expression of ESR1 and various ESR1 effector genes in breast cancer patients and breast cancer cell lines." (PMID 30647855, 2018). "Together with results acquired above, we hypothesized that the suppressive roles of miR-129 may be attributed to the active pathway of miR-129/ESR1/Let-7b in groups of stem-like cells in breast cancer, dependent on the existence of cyclin d1/DICER1." (PMID 29262559, 2017). "Within hypermethylated c-HMRs, we detected previously reported frequent DNA hypermethylation at gene promoters such as MGMT in glioblastoma, NSD1 in neuroblastoma, ESR1 in breast cancer, GSTP1 in prostate cancer and the promoter hypermethylation of RASSF1 in various cancer contexts." (PMID 28581523, 2017). "Here, we describe the characterization, at the transcriptional level, of the intra-tumor topography of two prominent breast cancer biomarkers and drug targets, epidermal growth factor receptor 2 (HER2) and estrogen receptor 1 (ER) in 49 archival breast cancer samples." (PMID 28423635, 2017). "This is especially noteworthy in view of our previous finding, that high levels of APOBEC3B were only associated with poor prognosis in ESR1-positive primary breast cancers, and not in ESR1-negative cases." (PMID 28141868, 2017). "ESR1 mutations occur in endocrine-resistant patients but have not yet been reported in in vitro models of breast cancer." (PMID 29192207, 2017).
breast cancer (continued). "This can be presumed that TH could be a viable option to mediate hematological parameter, and expression of Caspase-9, Apaf-1, E2, Bcl-xL and ESR1 against breast cancer." (PMID 28399853, 2017). "Additionally, the Urothelial-like subtype is to some extent analogous to the ESR1 expressing breast cancer “Luminal A” subtype that responds less well to HER2 targeted therapy." (PMID 28388586, 2017). "Furthermore, the authors also observed that changes in ERα and DNMTs were related to the changes in DNA methylation of the ERα (Esr1) gene, which was also observed in human breast cancer cells after DBP treatment." (PMID 28567415, 2017). "Several Gata3 target genes have been proposed, including CCND1, CDKN2C, MUC1, and ESR1, however the target genes affected by Gata3 mutations in human breast cancers have not been elucidated." (PMID 29262572, 2017). "Moreover it will be of interest the role of fulvestrant in estrogen receptor (ESR1) mutant breast cancers." (PMID 28903361, 2017). "In addition, genomic alterations in many oncogenic genes have been identified in ER-positive advanced breast cancers such as PIK3CA mutations, FGFR1 and CCND1 gene amplifications, and more recently ESR1 mutations." (PMID 28978004, 2017). "Previous data on ESR1 methylation in breast cancer is inconsistent." (PMID 28403857, 2017). "About 70% of all breast cancers are estrogen receptor alpha positive (ER+; ESR1)." (PMID 29228577, 2017). "Based on the 1000 Genomes Project European reference data, the 101 and 23 SNP-sets correspond to four and two independent SNPs, respectively, thereby suggesting significant genetic overlap between overall breast cancer and endometriosis (P=0.02; binomial test) at the 6q25.1 (ESR1) locus." (PMID 28537267, 2017). "Mutations in the estrogen receptor alpha (ERα) 1 gene (ESR1) are frequently detected in ER+ metastatic breast cancer, and there is increasing evidence that these mutations confer endocrine resistance in breast cancer patients with advanced disease." (PMID 28535794, 2017). "Over 70% of breast cancers (BC) are estrogen receptor-α (ESR1) positive at diagnosis." (PMID 29192207, 2017). "Also, miR-22 directly inhibited ESR1 mRNA and protein expression in breast cancer cell lines and clinical biopsies." (PMID 27834829, 2016). "Recent studies have shown that ESR1 mutations can be detected in metastatic ER+ breast cancer tissues but generally not in primary tumour tissues collected before the initiation of endocrine therapy." (PMID 27174596, 2016). "However, approximately 30% of invasive breast cancers are hormone-independent because they lack ERα expression due to inactive ESR1 promoter." (PMID 27884978, 2016). "Similar results have been reported in human breast cancer for both ESR1 and PGR expression." (PMID 27649560, 2016). "The ER, in particular ERα (encoded by the ESR1 gene), has been widely studied in breast cancer." (PMID 27539783, 2016). "Similarly the recurrent ESR1 truncations we report appear to be much more frequent in primary endometrial carcinoma than in primary breast cancers." (PMID 27160768, 2016). "To measure the amount of effort that a country X put into a gene Y, we divided the number of abstracts from country X which mentioned gene Y, by the number of papers published from country X. All of top 10 countries for breast cancer research put most of their effort into ESR1 and ERBB2." (PMID 27112211, 2016). "We have identified 36 TFs whose regulons are significantly enriched for genes associated with breast cancer risk loci (termed “risk TFs”), and four of these risk TFs (ESR1, FOXA1, GATA3 and SPDEF) have been identified as MRs of FGFR2-mediated risk in breast cancer." (PMID 27997592, 2016). "The top two most mentioned genes in the breast cancer abstracts were ESR1 and ERBB2." (PMID 27112211, 2016).
breast cancer (continued). "The most common classification system for breast cancer is presently based on histological type, tumor grade, lymph node status and the presence of predictive markers such as estrogen receptor alpha (ESR1), progesterone receptor (PGR) and epidermal growth factor receptor (HER2)." (PMID 26783963, 2016). "Such stratification based on HYAL1 expression in concordance with ERα status in breast cancer subtypes is suggested with our results showing significant lower expression of HYAL1 in breast tumors highly expressing ESR1, such as luminal A and luminal B subtypes." (PMID 27764788, 2016). "According to correlation analyses between gene expression and phosphorylated protein expression in both cell lines and tumors, significant results are found that important drug targets in breast cancer, such as ESR1, PGR, HER2, EGFR and AR show high correlated mRNA and protein levels." (PMID 27556158, 2016). "We next sought to determine whether ESR1-enhancer hypermethylation was indicative of breast cancer subtype." (PMID 26169690, 2015). "In addition, we demonstrate that the methylation status of these regulatory regions is associated with endocrine resistance in human disease, thus providing a novel mechanism by which endocrine response is abated in ESR1-positive breast cancers." (PMID 26169690, 2015). "Apart from the fact that the role of the PPARG/RXRA heterodimer in urothelial cancer is exchanged with the ESR1 hormone receptor in breast cancer, the key transcription factors FOXA1 and GATA3 are downregulated in the basal/SCC-like subtypes of both tumor types." (PMID 26008846, 2015). "Particularly, GABRP increased (P = 0.005) while ESR1 decreased (P = 0.009) in young breast cancer." (PMID 25990390, 2015). "In addition to ESR1, this region includes three previously annotated genes, C6orf96, C6orf211 and C6orf97, all of which are co-regulated in breast cancer cells." (PMID 25923108, 2015). "First, in a previous study we could show that ESR1 is an independent prognostic factor in metastatic NSCLC similar to breast cancer." (PMID 25928859, 2015). "We speculate that miR‐19a might be co‐expressed with lncRNA‐DLEU1 to co‐regulate the expression of ESR1, which influences the occurrence and development of breast cancer cells with different levels of ER expression." (PMID 26416600, 2015). "Future studies should also address whether there is efficacy of combining epigenetic therapies with endocrine treatment in preM breast cancer patients, possibly using ESR1 methylation as a predictive biomarker." (PMID 26251034, 2015). "Therefore, the results warrant further evaluation of antihormonal treatment in a subgroup of patients with lung cancer (ESR1 high lung cancer) in analogy to ER/PR positive breast cancer." (PMID 25928859, 2015). "Thus, in analogy with what was demonstrated for ESR1 in breast cancer, a combination of SPIB type I and type II TF binding sites is needed to regulate gene expression in ABC DLBCL cells." (PMID 26099425, 2015). "Interestingly, in ER- breast cancer, ESR1 (ERα), RELA, SP1, and AR exhibit the highest degree in the network." (PMID 25996148, 2015). "For breast cancer, we report enrichment for ESR1 DNA bindings in gained enhancer loci in MCF-7 cell line relative to MCF-10A cell line, as well as NR2F2 which encodes a member of the steroid thyroid hormone receptor, involved in apoptosis and increased proliferation." (PMID 25477382, 2015). "ESR1 point mutations conferring hormonal therapy resistance, on the other hand, were recently found in breast cancer metastases but not in matching primaries." (PMID 26439695, 2015).
breast cancer (continued). "Notably, GABRP and ESR1 previously reported to be related to young breast cancer were included in these differentially expressed genes and validated by qRT-PCR, proving the reliability of our data mining and allocation of samples." (PMID 25990390, 2015). "The second variant at 6q25.1 (rs60705924) is located in CCDC170/ESR1 region, a well-established breast cancer locus, but its putative functions are not well defined." (PMID 26036842, 2015). "Further characterization of ESR1-responsive enhancer methylation in endocrine-resistant disease will hereafter be an important area of future investigation, as will be the assessment of its potential predictive and prognostic application in breast cancer." (PMID 26169690, 2015). "First, using the merged dataset we visually inspected the epithelial expression of ESR1 in breast cancer; the results of unsupervised hierarchical clustering of samples using all genes; and a scatterplot of samples along the first two principal components of the gene expression data." (PMID 26087699, 2015). "For instance, AR and ESR1 are well-established endocrine receptors in breast cancer." (PMID 26618778, 2015). "Prospective clinical trials evaluating the benefits of dose escalation of anti-estrogens such as tamoxifen and fulvestrant may therefore be warranted in ESR1 mutant breast cancers that have failed standard-dose anti-estrogen therapy." (PMID 25928204, 2014). "CCND2 and ESR1 are signature genes that are frequently methylated in breast cancer." (PMID 24586797, 2014). "An example is shown with estrogen receptor 1(ESR1), a common marker used in breast cancer research." (PMID 24271388, 2014). "Moreover, re-expression of ESR1 re-sensitized breast cancer cells to the ER-targeted therapy tamoxifen in vitro." (PMID 25410383, 2014). "As a result, the patients harboring ESR1->AKAP12 fusion may exhibit different responses to breast cancer hormone therapy." (PMID 24727804, 2014). "That these tumors are more aggressive is also suggested by recent data using anti-phospho S118 ESR1 to identify cases where the ERα pathway is active; mutation of this site leads to more aggressive cell behavior in MCF7 breast cancer cells (and references therein)." (PMID 24523870, 2014). "Epigallocatechin-3-gallate, a major catechin found in green tea extract, was found to induce apoptosis in breast cancer via inhibiting expression of genes such as VEGF (vascular endothelial growth factor) and it was shown to induce re-expression of ESR1 in breast cancer cells." (PMID 25410383, 2014). "In this report, the estrogen receptor (ESR1) had defined the relation of breast cancer." (PMID 25054138, 2014). "This could be of considerable interest because such an easily measured analyte (ESR1 DNA methylation in peripheral blood) can serve as biomarker, and probable therapeutic target against breast cancer." (PMID 24495356, 2014). "We note that ESR1 rs2234693 is not in linkage disequilibrium with the SNPs near the ESR1 gene that were associated with breast cancer risk in several genome wide association studies." (PMID 23935996, 2013). "If we focus on breast cancer samples and ignore the rest, we see that almost all breast cancer samples are ESR1 unmethylated, and their ESR1 expression can be either high or low, which does not contradict with the concept that methylation turns off the expression." (PMID 23742247, 2013). "We did not observe an association between potential functional genetic polymorphisms in the estrogen pathway, SHBG rs6259, ESR1 rs2234693, CYP19 rs10046 and rs4775936, and UGT1A1 rs8175347, or the progesterone pathway, PGR rs1042838, with the risk of breast cancer." (PMID 23935996, 2013). "Pharmacological down-regulation of ESR1 may be effective in treatment and prevention of breast cancer, ovarian cancer, colon cancer, prostate cancer, and endometrial cancer." (PMID 23430930, 2013).
breast cancer (continued). "Mutations in ESR1 occur in approximately 1% of primary breast tumors, however were found in 10% of breast cancer metastases but not in the autologous primary tumors." (PMID 24058649, 2013). "Therefore, it is expected that any gene subset predicting clinical behavior of breast cancer would contain ESR1 and/or PGR, and indeed this was shown earlier." (PMID 23819905, 2013). "Tumors that have amplification of ESR1 rely more on endogenous estrogen and thus estrogen-driven mitogenic effect could be manifested in general population of breast cancer patients, independently of tamoxifen treatment." (PMID 23951298, 2013). "We report deleted ESR1 cases in 15.7%, an incidence which is higher than the one reported by Ejlertsen (4.2%), though in agreement with preclinical observations showing gene deletion in four out of six breast cancer cell line." (PMID 23923010, 2013). "We demonstrated that loss of pRb in human breast cancer cells or human/mouse primary mammary cells, but not the two related family members p107 and pRb2/p130, decreases the expression of the ESR1 protein." (PMID 23900261, 2013). "The relevance of such subtype-specific targets has been exemplified by ESR1 (estrogen receptor α) for luminal-subtype breast cancers; these cancers share not only clinical features such as prognosis and the response to chemotherapy, but also the pattern of gene expression." (PMID 23666744, 2013). "Histological analyses of different breast cancer subtypes showed a prevalence of pRb loss in ESR1 negative tumors with a high frequency of occurrence in triple-negative breast cancer subtypes." (PMID 23900261, 2013). "The issue of ESR1 gene amplification in breast cancer has recently gained a lot of interest." (PMID 23951298, 2013). "ESR1 (estrogen receptor 1) localizes to the nucleus and plays a role in tissues such as bone, and is involved in pathological processes including osteoporosis, endometrial cancer, and breast cancer." (PMID 23731710, 2013). "To illustrate the utility of the TraceRNA algorithm for breast cancer study, we also focus on the genes interacted with the estrogen receptor alpha, ESR1, with GBmiRs including miR-18a, miR-18b, miR-193b, miR-19a, miR-19b, miR-206, miR-20b, miR-22, miR-221, miR-222, miR-29b, and miR-302c." (PMID 23573084, 2013). "The majority (70-80%) of breast cancer shows an over-expression of estrogen receptor alpha (ESR1)." (PMID 23627572, 2013). "There is a growing body of evidence that the N-terminal domain may have a role in tumor suppression and our work highlights its importance in the regulation of ESR1 activity with a direct consequence in the response of breast cancer therapy." (PMID 23900261, 2013). "Moreover, in a recent overview of data from a number of publications studying ESR1 gene dosage in breast cancer, PCR was shown to give the most coherent results across different studies." (PMID 23951298, 2013). "This suggests ESR1 as an interesting candidate gene for mammary tumours in dogs as well." (PMID 23574728, 2013). "Therefore, we investigated HER2 and ESR1 mRNA levels in core biopsies of HER2-positive breast carcinomas from patients treated within the neoadjuvant GeparQuattro trial." (PMID 23391338, 2013). "Moreover a study by MARIE-GENICA Consortium suggested that higher risk were observed in subjects having combined genotypes of both ESR1 and ESR2 genes which modified risk associated with estrogen monotherapy used in breast cancer." (PMID 22808109, 2012). "Hierarchical clustering analysis of 157 breast cancers using the intrinsic gene subset also revealed that 94% of triple-negative tumors were clustered together, harboring high expression of basal marker genes and low expression of the ESR1 gene." (PMID 23049873, 2012). "Microsatellites in the estrogen receptor (ESR1, ESR2) and androgen receptor (AR) genes have been hypothesized to be predisposing factors for breast cancer but the mechanisms are unknown." (PMID 22792352, 2012).